INS (insulin)
Diseases named in the same sentence as INS in open-access papers (continued):
Sharing a sentence is not in itself a finding about the gene and the disease.
diabetes (continued). "Gene therapy, which utilizes the plasma DNA or virus to induce insulin expression, could offer an alternative therapy for diabetes." (PMID 33802091, 2021). "Magnesium might affect insulin secretion, peripheral insulin sensitivity, insulin signaling, insulin-signaling kinases, low-grade systemic inflammation, carbohydrate and energy Metabolism, which lead to IR and diabetes mellitus." (PMID 34248844, 2021). "A recent analysis of PCI patients from New York confirmed these findings in more actual data: At one year, diabetes was associated with a 2.1× elevation in adverse event rates (MACE) in insulin-treated DM (ITDM) and with a HR of 1.27 in non-ITDM after PCI." (PMID 34436225, 2021). "For example, intake of other macronutrients including fat or protein may result in hyperglycemia and poor glycemic control when insulin dosing is based solely on carbohydrate counting as noted in the standard diabetes guidelines of the U.S. and Canada." (PMID 33918343, 2021). "Most felt taking insulin would mark a deterioration in diabetes control." (PMID 34120310, 2021). "Anxiety has been attributed to fear of insulin injection and is common among people with diabetes." (PMID 35002853, 2021). "The role of LPCs in the context of diabetes has been unraveled by a seminal experiment in which diabetic mice showed dose-dependent reduction of blood glucose levels compared to the hypoglycaemic activity of insulin." (PMID 34072220, 2021). "Diabetes, referred to as Diabetes mellitus, is a disorder in individuals with high blood glucose (blood sugar) due to the lack of insulin production and/or the improper response of the body’s cells to insulin." (PMID 33671354, 2021). "Moreover, preclinical and clinical trials are required to determine if MCS will be beneficial in the context of MetS/IR and/or T2DM, including in the study of leptin-based and insulin-derived models of diabetes." (PMID 34279477, 2021). "Exploring des‐acyl ghrelin's influence on the expression of RBP4, which has been shown to reduce insulin sensitivity, leading to diabetes, revealed that des‐acyl ghrelin treatment of C2C12 cells leads to a time‐ and dose‐dependent increase in the mRNA levels of RBP4." (PMID 33463908, 2021). "We are also unable to confirm whether our patients received pre-treatment for hyperglycemia or routine insulin for diabetes mellitus prior to recorded glucose, which may have influenced admission glucose and calculated aGG levels." (PMID 34887824, 2021). "Diabetes mellitus results from defects in either insulin secretion or action or both." (PMID 35223819, 2021). "In addition to insulin therapy, diabetes management should include education, support, and access to psychological services." (PMID 34828602, 2021). "Our previous studies reported that berberine could reduce ischemia/reperfusion-induced myocardial apoptosis, improve mesenteric artery insulin sensitivity in diabetes, and reduce diabetic myocardial damage by inhibiting IGF-1R signaling." (PMID 35008753, 2021). "Next we tested if the effect of insulin signaling measure was differential by diabetes status." (PMID 33858515, 2021). "In a previous study, intranasal insulin therapy improved cognitive function and slowed cognitive decline and the insulin sensitizer, pioglitazone, showed time- and dose-dependent effects for preventing the development of dementia in patients with diabetes." (PMID 33402193, 2021). "This increased insulin sensitivity could explain the low incidence of diabetes in patients with defective TC-NER, despite having a progressive aging phenotype." (PMID 33493548, 2021). "Possible benefits of these diets are the improvement of glycemic control, the reduction of Hb1Ac levels and insulin requirement that may help to improve psychological outcomes, e.g., reducing diabetes distress and depressive symptoms." (PMID 34444784, 2021). "Thus, PTP1B inhibitors are pursued as insulin sensitizing antidiabetic targets against type 2 diabetes mellitus and obesity." (PMID 35008779, 2021).
diabetes (continued). "Moreover, Zn is known to be crucial for the synthesis, storage, and release of insulin and is related to diabetes and MetS." (PMID 33562398, 2021). "In contrast, chronic caloric starvation, with reduced serum insulin concentrations is not known to cause a diabetes-like retinopathy." (PMID 33915127, 2021). "A rigorous three-step matching algorithm that considered the initiation date of basal insulin, previous exposure of antidiabetic treatments, comorbidities, diabetes severity and complications, and concomitant medications was applied to achieve the between-group comparability." (PMID 33602950, 2021). "Hypometabolic obesity (LMO, 15% patients) was characterized by extremely high glucose, decompensated insulin secretion, and the worst glucolipid metabolism (diabetes: AOR 105.85 to MHO, 95%CI 42.00-266.74; metabolic syndrome: AOR 13.50 to MHO, 95%CI 7.34-24.83)." (PMID 34335479, 2021). "Genome expression in insulin signaling and integrated pathology can alter any of these genes that might develop clinically important insulin resistance and diabetes." (PMID 35046895, 2021). "Insulin treatment is frequently used in persons with diabetes and liver cirrhosis." (PMID 34118892, 2021). "Patients with diabetes were treated with insulin titration algorithm." (PMID 33916210, 2021). "In addition to its role in diabetes, the recent literature indicates that insulin acts on several key organs in the body, including the brain, heart, kidney, bone, skin, and hair follicles, to perform important physiological roles." (PMID 34203830, 2021). "Among patients with diabetes, 176 (81%) were on metformin, and 38 (18%) were insulin-dependent." (PMID 34372849, 2021). "The integration of insulin pumps with other diabetes technologies developed in the past decade has opened the gateway to methods of optimally controlling blood glucose and minimising user burden, including closed-loop insulin delivery." (PMID 33950566, 2021). "However, our understanding at the molecular level of mechanisms linking diabetes to stroke is less well understood, specifically the relation of resistance to insulin, a key characteristic of diabetes, to cerebrovascular disease." (PMID 33858515, 2021). "Diabetes mellitus is a chronic metabolic disease caused by an absolute or relative lack of insulin and/or reduced physiological insulin activity, resulted in hyperglycemia and abnormalities in carbohydrate, protein, and fat metabolism." (PMID 34158818, 2021). "Finally, evaluating the short and long-term cost savings from reducing or discontinuing insulin and improving diabetes control compared with the cost of attending an intensive lifestyle program should be undertaken." (PMID 34458301, 2021). "In the landmark trial of the United Kingdom Prospective Diabetes Study (UKPDS), metformin, relative to diet alone or other glucose-lowering agents such as sulfonylureas and insulin, was shown to reduce the risk of cardiovascular events and mortality in obese patients with newly diagnosed T2D." (PMID 34332584, 2021). "Furthermore, due to the progressive nature of T2D, many patients eventually require and benefit from insulin therapy, and thus sound evidence on the long-term effects of basal insulin is needed for optimizing clinical diabetes care." (PMID 33602950, 2021). "The primary treatment for this type of diabetes is based on regular insulin injections." (PMID 34201756, 2021). "Fasting insulin concentrations decreased from 10 to 13 weeks of age in the dbdb group, but they were maintained in the dbdb+CR group, indicating that CR can inhibit the reduction of fasting blood insulin concentrations shown in the late stage of diabetes." (PMID 33916828, 2021). "The authors found that the prepared nanoparticles containing insulin may have promising possibilities for the transdermal delivery of diabetes chemotherapy." (PMID 33466845, 2021).
diabetes (continued). "As far as we know, few studies have focused on early variations in insulin sensitivity in young people due to the difficulties in distinguishing pre-diabetes conditions in general healthy populations for variabilities in clinical parameters and the effect of lifestyle factors." (PMID 34243726, 2021). "Bay leaves have also shown that display insulin-enhancing activity in vitro, however these enhance glucose metabolism and the overall condition of individuals with diabetes not only by hypoglycemic effects but also by improving lipid metabolism, antioxidant status, and capillary function." (PMID 33520200, 2021). "At the age of 8 years, he developed diabetes, which was controlled by insulin." (PMID 33472655, 2021). "Previous studies have confirmed that dietary fiber is one of the most important factors in maintaining normal insulin sensitivity in human tissue cells, and inadequate intake can lead to a high incidence of diabetes mellitus." (PMID 34276373, 2021). "This decrease is similar to that reported in vascular disease, including diabetes, and may explain at least in part the insulin remodeling of cardiomyocytes morphology found in our experiments." (PMID 34835942, 2021). "Current treatments for diabetes are based on the administration of exogenous insulin or insulin analogs, or treatment with agents that stimulate insulin secretion by β-cells, improve insulin sensitivity, promote glucose excretion, or delay carbohydrate digestion." (PMID 33921851, 2021). "We have found that β cell function defects may be the main mechanism for the development of diabetes in WSS, which suggests that insulin should probably be the main treatment for patients with WSS when diabetes occurs." (PMID 35002959, 2021). "Stratifying patients by medication- or insulin-required diabetes mellitus may obtain more accurate results." (PMID 33435881, 2021). "According to the WHO and the American Diabetes Association (ADA), DM is defined as an endocrine metabolic disease characterized by prolonged and persistent hyperglycemia caused by either inadequate insulin production or insulin action or a combination of both." (PMID 34564146, 2021). "Many studies have indicated that the tumor necrosis factor alpha (TNF-α) may affect insulin action thus leading to the development of diabetes." (PMID 34067027, 2021). "Additionally, APO C-III regulates triglyceride metabolism, negatively affects calcium handling and insulin sensitivity, and stimulates pancreatic beta-cell apoptosis, leading to insulin resistance and diabetes mellitus." (PMID 34299261, 2021). "Also, most studies included instructions for people with insulin-treated diabetes to adjust insulin use to avoid (nocturnal) hypoglycaemia prior to clamping." (PMID 33566134, 2021). "In diabetes mellitus type 2 diabetes, underlying severe illness is almost always the direct cause of both the DKA and ensuing death; while in diabetes mellitus type 1 diabetes, DKA is most often caused by missed insulin doses but death is rare with prompt treatment." (PMID 34702335, 2021). "There are three main types of diabetes: type 1 diabetes (caused by the body's failure to produce insulin), type 2 diabetes (resulting from insulin resistance), and gestational diabetes (which occurs in pregnant women without previous diagnosis of diabetes)." (PMID 33688505, 2021). "The latest advances in diabetes therapy combine sensors for continuous glucose monitoring and insulin pumps with computerized control algorithms, thereby enabling automated adjustments to insulin delivery in response to the user’s changing glucose levels." (PMID 34096874, 2021). "This means that BMP has potential as an oral plant insulin for the treatment of diabetes." (PMID 32354072, 2020). "The combination of CLA and Cr-Met reduced IMF, and the combinations of CLA and CS and Cr-Met and CS reduced the fat content among muscle cells, which may provide some insights into the study of insulin sensitivity and diabetes." (PMID 32832551, 2020).
diabetes (continued). "Also, it is discussed about some controversies regarding the use of the insulin analogues in the treatment of patients with diabetes mellitus." (PMID 32002701, 2020). "It is associated with intra-uterine growth retardation, erythroblastosis fetalis, perinatal asphyxia, maternal diabetes mellitus (gestational or insulin dependent) and after the maternal administration of drugs such as sulphonylureas, and intravenous glucose infusions during labor." (PMID 32185602, 2020). "Insufficient insulin secretion leads to elevated levels of blood glucose resulting in diabetes." (PMID 33164744, 2020). "In addition, it was reported that PPARγ was an important receptor in the treatment of diabetes, and its activation reduced hyperglycemia by increasing sensitivity to peripheral insulin." (PMID 32265835, 2020). "Type 2 diabetes mellitus (T2DM) is an important endocrine and metabolic disorder, which is caused by the impairment of insulin's ability to reduce blood glucose level due to the deficiency of insulin release and action, leading to hyperglycemia, which is also the main clinical feature of T2DM." (PMID 32714403, 2020). "In contrast, decreased insulin sensitivity in men without diabetes is apparently associated with reduced small intestine enteric mass." (PMID 32292494, 2020). "Moreover, 75.4% of subjects were insulin-resistant, a situation presumably the consequence of obesity itself, but also of inadequate diabetes care and a dietary pattern characterized by little variability and poor nutritional quality." (PMID 32098332, 2020). "Based on these findings, we suggest that PDAC initiation might lead to selective depletion of β-cells, which could ultimately result in decreased insulin secretion and attendant hyperglycemia and diabetes." (PMID 32371554, 2020). "Another study shows the involvement of miRNA in insulin and diabetes regulation." (PMID 33230925, 2020). "Our study included careful screening and exclusion for existing diabetes and sleep disorders, assessment and adjustment for habitual sleep timing, as well as the assessment of insulin sensitivity using both a glucose tolerance test and fasting measures to confirm associations." (PMID 32079066, 2020). "Type 2 diabetes mellitus (T2DM) arises out of impaired insulin secretion and insulin resistance." (PMID 32148647, 2020). "Finally, DBMSC expression of genes involved in insulin secretion and prevention of diabetes was also modulated by glucose." (PMID 32077075, 2020). "A previous study reported that CDR1as can regulate insulin secretion and may represent a new target for improving β-cell function in diabetes." (PMID 32182790, 2020). "Although the underlying mechanisms by which diabetes promotes AD pathogenesis have not been elucidated, previous research supports multi-faceted dysfunction caused by diabetes, including neuronal insulin signaling, mitochondrial dysfunction, and inflammation." (PMID 31992349, 2020). "This may be especially helpfulfor patients who may need reinforcement of administration techniques for medicationslike albuterol and insulin to prevent patients from being readmitted from conditionslike asthma and diabetes." (PMID 32547752, 2020). "Therefore, in addition to other metabolic syndrome factors such as hyperglycemia, dyslipidemia, hypertension, and vascular complications, impaired insulin signaling in diabetes likely contributes to the development of neurodegenerative disorders." (PMID 33536868, 2020). "Strengthening the causal link between deregulated glycaemic homeostasis, including insulin secretion and resistance and AD, is the recent identification of a newly indicated form of diabetes named “type 3” diabetes that is characterized as a brain-insulin resistant state linked to AD." (PMID 31936865, 2020).
diabetes (continued). "It is known that disorders in insulin metabolism and consequently in glucose metabolism result in oxidative stress and inflammation, which lead to micro- and macrovascular dysfunctions and to the further development of diabetes and cardiovascular diseases." (PMID 32316129, 2020). "AID may present as a sudden onset of insulin deficiency, with symptoms and frequent ketosis, being the patient dependent on exogenous insulin just after the diagnosis-the so-called “classic type 1 diabetes mellitus” (T1DM)." (PMID 33292447, 2020). "Tight glycemic control and use of diabetes medications, especially insulin and sulphonylureas, could result in hypoglycemia." (PMID 32824748, 2020). "Additionally, during the analysed period, a lot of new molecules or medical devices (e.g., SGLT-2 inhibitors, insulin pumps, etc.)were introduced in diabetes treatment." (PMID 32575853, 2020). "In particular, XA was found to contribute to diabetes development by chelating complexes with insulin and exerting pathological apoptosis effects on pancreatic beta cells; furthermore, 3-HAA plays a key role in anti-inflammation and neuroprotection, demonstrating strong antioxidative properties." (PMID 33271740, 2020). "CTSS may be involved in the early dysregulation of glucose and insulin metabolism as higher serum CTSS was associated with decreased insulin sensitivity and an increased risk for developing diabetes." (PMID 32398133, 2020). "Insulin resistance or diabetes attenuates the normal regulatory response of VAT to insulin via down-regulation of mammalian target of rapamycin complex 2 (mTORC2) and phosphoinositide 3-kinase (PI3K) thereby promoting macrophage infiltration to VAT which leads to boost VAT inflammation." (PMID 31992764, 2020). "Our results strongly suggested the essential role of the insulin signaling pathway within osteoblast in diabetes, indicating the osteoblast could function as a target for diabetes." (PMID 32278305, 2020). "The extensive file of predicted targets of all microRNAs aberrantly expressed in whole peripheral blood of mothers with a history of GDM indicates that a large group of genes is involved in biological pathways related to insulin signaling, type 1 diabetes mellitus, and type 2 diabetes mellitus." (PMID 32244558, 2020). "A recent systematic review of 53 studies worldwide has highlighted the widespread problem of therapeutic inertia in diabetes—with delays common across all stages of treatment initiation and intensification, though most pronounced around the time of intensification to insulin." (PMID 32413037, 2020). "Our study suggests that consuming 25% of your total energy intake earlier in the day is associated with higher insulin sensitivity, irrespective of the total amount of calories consumed—even in people without diabetes." (PMID 32079066, 2020). "Larger studies are needed to establish the intriguing findings of this pilot study and to further explore the immediate, short-term, and intermediate effects of different insulin blood levels in euglycemia, in subgroups of sorted out patients with diabetes mellitus and its complications." (PMID 32308680, 2020). "In this regard and considering the fact that insulin is used as the last resort when the oral therapy is ineffective in patients with type 2 diabetes, longer periods of diabetes are expected in insulin-dependent patients resulting in a direct negative impact on the patients’ QoL." (PMID 32000785, 2020). "Therefore, neurodegenerative diseases have been described as the third type of diabetes or a brain insulin resistant state." (PMID 32575897, 2020). "Insulin treatment and having had a prior acute glycaemic event leading to an ED visit were major predictors of ED attendance for hyper and hypoglycaemia in a population of adults with diabetes." (PMID 32429960, 2020).